NLRP1 (NLR family pyrin domain containing 1)
Diseases named in the same sentence as NLRP1 in open-access papers (continued):
Sharing a sentence is not in itself a finding about the gene and the disease.
brain injury (3 papers, 2016 to 2023). Acute and chronic (see also brain INJURIES, CHRONIC) injuries to the brain, including the cerebral hemispheres, CEREBELLUM, and brain STEM. "Prior studies have shown that therapeutic targeting of the NLRP1 inflammasome attenuates the immune response and significantly improves histopathologic features associated with traumatic brain injury in rats (PMID: 19401709; 22781337)." (PMID 27199506, 2016). "We also present recent studies on NLRP1 as a target for the treatment of EBI, ischemic brain injury, TBI, and other types of brain injury, thus highlighting the perspective of NLRP1 as an effective mediator of catastrophic brain injury." (PMID 35707533, 2022).
cardiac hypertrophy (3 papers, 2022 to 2023). "It was found that the knockout of NLRP1 gene alleviates the occurrence and development of myocardial hypertrophy and inflammation in mice." (PMID 37214347, 2023). "In previous research, our research team found that the knockout of NLRP1 gene will inhibit MAPKs and NF- κ B signal pathway, thereby reducing the occurrence and development of myocardial hypertrophy and inflammation in mice." (PMID 37214347, 2023).
cognitive decline (3 papers, 2011 to 2024). "Studies in murine AD models also show that Aβ oligomers up-regulate NLRP1 inflammasome, which results in cognitive decline associated with the observed neuronal death." (PMID 37578928, 2023). "Studies in murine AD models indicate that the Nlrp1 inflammasome is indeed upregulated, and neuronal death is observed, leading to cognitive decline." (PMID 38658973, 2024). "Further studies are needed to determine whether the NLRP1 inflammasome-induced activation and increased IL-1β and IL-18 observed in our study influence deficits in synaptic transmission leading to cognitive decline." (PMID 22133203, 2011). "Thus, aging processes stimulate activation of the NLRP1 inflammasome and secretion of IL-1β and IL-18 that may contribute to age-related cognitive decline in the growing elderly population." (PMID 22133203, 2011).
colon adenocarcinoma (3 papers, 2022 to 2025). "The somatic mutation of eight risk PRGs (CASP4, GPX4, GSDMC, TLR3, NLRP1, PLCG1, IL18, and IRF1) hardly occurred in PAAD samples but were commonly observed in colon adenocarcinoma (COAD) and stomach adenocarcinoma (STAD) ones." (PMID 35000541, 2022).
Coronary Artery Disease (3 papers, 2023 to 2025). "According to the patients' coronary arteriosclerosis Gensini score, there were differences in serum NLRP1 levels among the control group, low-risk group, medium-risk group, and high-risk group." (PMID 37214347, 2023). "Serum NLRP1 levels increase with the severity of coronary artery disease (from healthy controls to UA to AMI)." (PMID 41189992, 2025). "This study systematically explored the association between NLRP1 and AMI for the first time and found that the serum NLRP1 level gradually increased with the severity of coronary heart disease, from the healthy controls to UA and then to AMI." (PMID 41189992, 2025). "Serum NLRP1 levels correlate with coronary heart disease severity, indicating inflammation and myocardial injury, and independently predict short-term MACE in AMI." (PMID 41189992, 2025). "Spearman correlation analysis of the serum NLRP1 level and Gensini score in patients with coronary artery disease showed that there was a correlation between serum the NLRP1 level and Gensini score (ρ = 0.580, P < 0.05)." (PMID 37214347, 2023). "To investigate the relationship between the severity of coronary atherosclerosis and serum NLRP1 levels in patients with coronary artery disease, we selected unstable angina, which is a common type of coronary artery disease." (PMID 37214347, 2023). "The results suggest that NLRP1 is closely related to the severity of coronary artery disease in patients with UA." (PMID 37214347, 2023). "The process of coronary atherosclerosis and coronary artery disease is closely related to inflammation, but the relationship between NLRP1 and coronary atherosclerosis needs further exploration." (PMID 37214347, 2023). "At present, there are few studies on NLRP1 and coronary arteriosclerosis, and there is no systematic and comprehensive elaboration on its mechanism." (PMID 37214347, 2023).
cutaneous squamous cell carcinoma (3 papers, 2022 to 2025). "The downregulation of NLRP1 expression promotes the progression of human cutaneous squamous cell carcinoma." (PMID 36246601, 2022). "Recent evidence demonstrates that activation of NLRP1 in human skin supports the development of cutaneous squamous cell carcinomas (cSCCs) by inducing skin inflammation." (PMID 36293159, 2022).
glaucoma (3 papers, 2019 to 2021). Increased pressure in the eyeball due to obstruction of the outflow of aqueous humor. "In the eye, NLRP1 has been implicated in both DR and glaucoma with studies suggesting that upregulation of NLRP1 contributes to inflammation, ganglion cell death, and neovascularization." (PMID 33396676, 2020).
head and neck squamous cell carcinoma (3 papers, 2022 to 2025). A squamous cell carcinoma that arises from any of the following anatomic sites: lip and oral cavity, nasal cavity, paranasal sinuses, pharynx, larynx, and salivary glands. "Multi‐omics analyses further reinforce the prospect of NLRP1 serving as a biomarker for drug sensitivity in pancreatic adenocarcinoma and head and neck squamous cell carcinoma." (PMID 40237399, 2025). "Available studies previously reported that several scorch death‐related genes, including NLRP1 and NLRP3, play a key role in cancer immunity and may be employed as prognostic factors in pancreatic, breast, lung, and head and neck squamous cell carcinomas." (PMID 39318060, 2024).
HIV-1 infection (3 papers, 2023 to 2025). The type species of lentivirus and the etiologic agent of acquired immunodeficiency syndrome (AIDS). "In contrast, our findings suggest that Gag-Pol deletion or inhibition of PR activity only partially inhibited HIV-1-infection-induced NLRP1-mediated IL-1β secretion." (PMID 40920844, 2025). "In this study, we demonstrate that establishing productive HIV-1 infection and cytosolic viral icRNA expression activates NLRP1 inflammasome and IL-1β secretion in macrophages and iMGs." (PMID 40920844, 2025). "In humanized mice, the elevated levels of NLRP1 in the lymph nodes suggest an early host inflammasome activation response to HIV-1 infection." (PMID 38785555, 2024). "An investigation into single nucleotide polymorphisms (SNPs) within NLRP1, NLRP3, NLRC4, CARD8, CASP1, and IL1B genes revealed a significant association between two SNPs residing in NLRP3 and IL1B with increased susceptibility to HIV-1 infection." (PMID 38785555, 2024). "To show evidences of early inflammasome sensing of HIV-1 in huNSG mice upon HIV-1 infection, we quantified mRNA expression of genes involved in inflammasome activation (NLRP3, NLRP1, NLRC4, AIM2, IFI16, ASC, CASP1, IL1Β, and IL18) in hCD45+ cells from multiple tissues collected at necropsy." (PMID 36800238, 2023).
Hyperglycemia (3 papers, 2017 to 2025). An increased concentration of glucose in the blood. "The NLRP1 inflammasome is activated by hyperglycemia-associated DAMPs, triggering caspase-1 autocleavage and subsequent release of IL-1β/IL-18, which drives inflammatory responses." (PMID 40538805, 2025). "Hyperglycemia-induced endoplasmic reticulum (ER) stress further elevates NLRP1 levels via ATF-4 activation, leading to the activation of MAPK, NF-κB, and TGF-β/Smad signaling pathways, thereby promoting fibrogenesis and tissue injury." (PMID 40538805, 2025). "A study suggested that hyperglycemia can lead to activation of NLRP1 inflammasome and then contribute to neuron inflammation." (PMID 31088900, 2019).
Hypertension (3 papers, 2016 to 2023). The presence of chronic increased pressure in the systemic arterial system. "Patients who had improved hypertension 6 months after surgery presented with increased expression levels of the inflammasome activation components (ASC, P2X7, and IL18R), cytokines (CCL8, CXCL2, IKKA, and IL6R), NOD-like receptors (NLRP1), and cell cycle/DNA regulators (TGFb)." (PMID 37867510, 2023).
Insulin resistance (3 papers, 2018 to 2025). Increased resistance towards insulin, that is, diminished effectiveness of insulin in reducing blood glucose levels. "Taken together, these findings suggest that inflammasomes, including NLRP3, AIM2, NLRP1, NLRP6 and NLRC4 inflammasomes are involved in the regulation of insulin resistance, pancreatic β-cell health and diabetes." (PMID 40433411, 2025). "Studies suggest that NLRP1 and NLRP3 activity levels alter metabolic homeostasis and can thereby contribute to glucose intolerance and insulin resistance." (PMID 29515457, 2018).
intracerebral hemorrhage (3 papers, 2023 to 2025). A cerebrovascular disorder characterized by bleeding into one or both cerebral hemispheres including the basal ganglia and the cerebral cortex. "NLRP1 mediates inflammation following intracerebral hemorrhage, and NETs promote NLRP1-mediated neuronal pyroptosis." (PMID 41353157, 2025). "CCR5 activation promotes NLRP1-dependent neuronal pyroptosis after intracerebral hemorrhage; however, our study identified a reduction of necrosis, neurodegeneration, organ degeneration, and degeneration of the brain in TBI mice treated with CCL5." (PMID 39285280, 2024). "This study is performed to explore the role of P2X4 in intracerebral hemorrhage (ICH) and the association between P2X4 and the NLRP1/Caspase-1 pathway." (PMID 37652931, 2023).
leukemia (3 papers, 2015 to 2022). A malignant (clonal) hematologic disorder, involving hematopoietic stem cells and characterized by the presence of primitive or atypical myeloid or lymphoid cells in the bone marrow and the blood. "NLRP1 is highly expressed in leukemia patients and can form a large signal-induced multiprotein complex, which plays a crucial role in the development of leukemia." (PMID 29214170, 2017). "Notably, the transcription factor CREB has been described to induce NLRP1 expression in leukemia cells." (PMID 26086088, 2015).
lung squamous cell carcinoma (3 papers, 2022 to 2025). "However, although NLRP1 was also decreased in lung squamous cell carcinoma (LUSC), it did not have an effect on prognosis." (PMID 39258674, 2024).
mesothelioma (3 papers, 2012 to 2025). A usually malignant and aggressive neoplasm of the mesothelium which is often associated with exposure to asbestos. "This study proposes to evaluate the impact of known NLRP3 and NLRP1 polymorphisms in the individual susceptibility to asbestos-induced mesothelioma in subjects from a hyperendemic area for MM." (PMID 23031505, 2012). "However we believe that this strong association between the rs12150220 polymorphism in NLRP1 and asbestos-mesothelioma development emphasizes once more the role of inflammation and inflammasome in tumorigenesis events." (PMID 23031505, 2012). "Our findings, being controversial with respect to another study on Italian patients, do suggest the need of further studies to unravel the contribution of NLRP1 and NLRP3 in susceptibility to mesothelioma." (PMID 26236392, 2015). "Additionally, The DFS analysis indicated that reduced NLRP1 expression is associated with poorer DFS in CHOL, KIRC, and Mesothelioma (MESO)." (PMID 40237399, 2025). "Although NLRP3 SNPs was not involved in mesothelioma predisposition, these data proposed NLRP1 as a novel factor possibly involved in the development of mesothelioma." (PMID 23031505, 2012). "We analyzed NLRP3 rs35829419, rs10754558 SNPs and NLRP1 rs2670660, rs12150220 SNPs in 134 Italian patients with mesothelioma, in 256 healthy controls and in 101 individuals exposed to asbestos with no mesothelioma at the age of the enrollment." (PMID 23031505, 2012).
myeloid leukemia (3 papers, 2014 to 2020). A clonal proliferation of myeloid cells and their precursors in the bone marrow, peripheral blood, and spleen. "It has been reported that dibutyryl-cAMP, a cAMP analogue, can induce NLRP1 expression in human myeloid leukemia cells, possibly through PKA-mediated CREB activation." (PMID 33396632, 2020). "Other studies in myeloid leukaemia cells proposed that NLRP1 and CREB (cAMP-response-element-binding protein) may contribute by modulating the response to pro-inflammatory stimuli." (PMID 24917880, 2014).
nodular melanoma (3 papers, 2018 to 2025). "Recent studies suggest that NLRP1 is highly expressed in females in some pathological states such as nodular melanoma, and may be related to female high-risk diseases." (PMID 33328952, 2020). "Recent studies showed that NLRP1 inflammasome was overexpressed in females under some pathological conditions such as nodular melanoma." (PMID 33328952, 2020). "In particular the presence of nodular melanoma (NM) was associated with NLRP3-rs35829419 and NLRP1-rs12150220." (PMID 30447690, 2018).
parasite infection (3 papers, 2016 to 2023). "Previously, we reported that parasite infection of murine macrophage cell lines or human fibroblasts stably expressing Lewis rat NLRP1 does not trigger cell death." (PMID 30622189, 2019). "Mice lacking ASC, NLRP1, and NLRP3 are highly susceptible to parasite infection." (PMID 27378827, 2016).
peripheral arterial disease (3 papers, 2021 to 2023). A disorder of the arteries supplying the upper and lower extremity and the visceral organs. "Despite the encouraging evidence on the role and potential therapeutic implications of NLRP1 inflammasome, especially in peripheral arterial disease, studies of direct or indirect inhibitors are largely lacking, constituting an important knowledge gap." (PMID 37765019, 2023). "Another study has reported that elevated levels of plasma triglycerides and very-low-density lipoprotein cholesterol of patients with AS, manifested as peripheral arterial disease, promoted activation of the NLRP1 inflammasome by NF-κB in human arterial ECs." (PMID 35464402, 2022). "More and more evidence suggests that NLRP1 may trigger the immune-inflammatory processes in arterial ECs and affect the vessel remodeling; thus, NLRP1 inflammasome inhibition may be a novel therapeutic approach to peripheral arterial disease." (PMID 35464402, 2022).
skin cutaneous melanoma (3 papers, 2022 to 2025). "On the other hand, the elevated expression of PANoptosis genes ZBP1, NLRP1(NLR family pyrin domain containing 1), CASP8, and GSDMD was beneficial in skin cutaneous melanoma." (PMID 38169587, 2024). "Conversely, high expression of PANoptosis genes was beneficial in skin cutaneous melanoma (SKCM), with ZBP1, NLRP1, CASP8 and GSDMD expression consistently having positive prognostic effects." (PMID 36329783, 2022).
squamous cell carcinoma (3 papers, 2024 to 2025). A carcinoma arising from squamous epithelial cells. "Moreover, a significant increase in squamous cell carcinoma proteins marker genes such as SerpinA1, SerpinA3 and EphB2 under the influence of UV radiation was observed in cells with efficiently functioning NLRP1 and NLRP3." (PMID 39839625, 2024). "Moreover, previous studies proved that increased NF-κB activity could suppress NLRP1 inflammasomes in squamous cell carcinoma." (PMID 39258674, 2024). "On the other hand, silencing the NLRP1 and NLRP3 gene changed the expression of these squamous cell carcinoma proteins marker genes as well as basal cell carcinoma proteins such as Gli1, Gli2, FOXO3A." (PMID 39839625, 2024).
temporal lobe epilepsy (3 papers, 2015 to 2024). A localization-related (focal) form of epilepsy characterized by recurrent seizures that arise from foci within the temporal lobe, most commonly from its mesial aspect. "In human temporal lobe epilepsy patients, Caspase 1 is often upregulated in the hippocampi of patients with temporal lobe epilepsy and silencing of Caspase 1 or NLRP1 produces neuroprotective and antiepileptic effects which is also consistent with our data." (PMID 38166692, 2024).
ulcerative colitis (3 papers, 2018 to 2023). An inflammatory bowel disease involving the mucosal surface of the large intestine and rectum. "We also show that, in patients with ulcerative colitis, increased NLRP1 in inflamed regions of the colon is associated with increased IFN-γ." (PMID 30214011, 2018). "NLRP1 gene expression has been found to be elevated in inflamed regions of ulcerative colitis patients’ colons." (PMID 37833958, 2023). "NLRP1 activity showed a positive correlation with IL-18 production and IFN-γ gene expression, which could exacerbate the inflammation response in ulcerative colitis." (PMID 37833958, 2023).
acute respiratory distress syndrome (2 papers, 2019 to 2021). Progressive and life-threatening pulmonary distress in the absence of an underlying pulmonary condition, usually following major trauma or surgery. "NLRP1-dependent pyroptosis in the lung alveolar macrophages has been shown to cause progressive lung damage that is similar to the one seen in acute respiratory distress syndrome." (PMID 34027315, 2021).
anemia (2 papers, 2013 to 2023). A reduction in the number of red blood cells, the amount of hemoglobin, and/or the volume of packed red blood cells. "Activation of NLRP1 induces pyroptosis in hematopoietic cells and inhibition of NLRP1 may play a protective role in individuals having blood disorders such as anemia and leukopenia and suffering from bacterial septic shock." (PMID 24032031, 2013).
basal cell carcinoma (2 papers, 2024 to 2025). A carcinoma involving the basal cells. "Additionally, a negative association was identified between NLRP1 transcriptional level and CAF in specific subgroups, such as HPV‐negative HNSC, BRCA basal cell carcinoma, BRCA HER2 positive, BRCA‐lumA, BRCA‐lumB, and SKCM metastasis based on the EPIC algorithm." (PMID 40237399, 2025).
breast adenocarcinoma (2 papers, 2014 to 2018). "NLRP1 overexpression can also induce apoptosis in breast adenocarcinoma cells." (PMID 30514293, 2018).
breast neoplasm (2 papers, 2017 to 2025). A benign or malignant neoplasm of the breast parenchyma. "Based on our research, we favor the hypothesis that NLRP1 may play a critical role in the tumorigenesis proliferation, migration, and invasion of human breast tumor." (PMID 29214170, 2017). "Expression of NLRP1 was high in 83% (60/72 specimens) of examined breast tumors." (PMID 29214170, 2017). "To date, the pattern of expression and function of NLRP1 in human breast tumor has not been elucidated." (PMID 29214170, 2017).
coronary atherosclerosis (2 papers, 2023 to 2025). Atherosclerosis of the coronary vasculature. "Our study laid the foundation for exploring the relationship between NLRP1 and coronary atherosclerosis and provided objective evidence support." (PMID 37214347, 2023). "The complex relationship network between NLRP1 and coronary atherosclerosis needs to be further explored, and the correlation between serum NLRP1 and coronary atherosclerosis needs to be further clarified." (PMID 37214347, 2023). "This experiment was based on the hospital to explore the correlation between the serum NLRP1 level and the severity of coronary atherosclerosis in patients undergoing coronary angiography." (PMID 37214347, 2023). "NLRP1 is closely related to coronary atherosclerosis and it can serve as an effective indicator for predicting UA." (PMID 37214347, 2023). "Serum NLRP1 levels were significantly higher in patients with multivessel disease than in controls and patients with single‐vessel disease, and serum NLRP1 levels were positively correlated with the severity of coronary atherosclerosis, consistent with the results of this study." (PMID 40387676, 2025). "The level of serum NLRP1 is positively correlated with the severity of coronary atherosclerosis." (PMID 37214347, 2023). "But up to now, there is no clinical study involving the relationship between coronary atherosclerosis and NLRP1." (PMID 37214347, 2023).